BRAF (B-Raf proto-oncogene, serine/threonine kinase)
Diseases named in the same sentence as BRAF in open-access papers (continued):
Sharing a sentence is not in itself a finding about the gene and the disease.
cutaneous melanoma (continued). "The Cancer Genome Atlas (TCGA) allowed the identification of four genetic subtypes of cutaneous melanoma, BRAF mutant (the most common condition responsible for more than 50% of cases), RAS mutant, NF1 mutant, and Triple Wild-Type." (PMID 28118616, 2017). "Several studies have shown that anti‐BRAF‐V600E IHC had a sensitivity and specificity over 95% in cutaneous melanoma." (PMID 28293477, 2017). "Hotspot mutations of the oncogenes BRAF and NRAS are the most common genetic alterations in cutaneous melanoma." (PMID 28797232, 2017). "Activating hot-spot mutations are mainly found in BRAF (codon V600) and in NRAS (codon Q61, and less frequently in the codons G12 and G13) genes, in 35–50% and 15–25% of cutaneous melanoma, respectively." (PMID 28668077, 2017). "There is evidence that the BRAF inhibition exerts an influence on immunological landscape of cutaneous melanoma." (PMID 26863566, 2016). "Both BRAF and CDKN2A mutations in cutaneous melanoma cells are characteristic of indirect UV-induced oxidative damage." (PMID 26850723, 2016). "In contrast, treatment with the BRAF inhibitors vemurafenib and dabrafenib is established for patients with BRAFV600E and BRAFV600K mutated disseminated cutaneous melanomas." (PMID 27520988, 2016). "• All patients with cutaneous melanoma should have their original tumour checked for BRAF gene status, and their subsequent targeted biological therapy based on this." (PMID 27841141, 2016). "Inhibition of BRaf signaling as a therapy for the 50% of cutaneous melanomas that are mutant BRAFV600E is confounded by a wide variety of mechanisms of resistance, both intrinsic and acquired." (PMID 26405815, 2015). "Recent combined data analysis from various reports so far has disclosed a prevalence of 5% for BRAF and 14% for NRAS oncogenic mutations in all types of mucosal melanomas, strikingly in contrast to the BRAF prevalence of 56–59% in cutaneous melanomas." (PMID 25695059, 2015). "The first is an open label phase 3 looking at dabrafenib plus trametinib versus vemurafenib alone in unresectable or metastatic BRAF V600E/K cutaneous melanoma (ClinicalTrials.gov, NCT01597908)." (PMID 24693430, 2014). "We analyzed BRAF state in 75 formalin-fixed paraffin-embedded (FFPE) samples of cutaneous melanoma metastases from 29 patients (age 62±25, male-to-female ratio 1.9)." (PMID 23555633, 2013). "We have previously reported differential activation of the MAPK and AKT/mTOR signalling pathways in uveal and skin melanomas harbouring, respectively, GNAQ and BRAF mutations." (PMID 23904987, 2013). "Our panel also included five cutaneous melanoma cell lines wild type for mutations in NRAS, BRAF, GNAQ and GNA11 and only one was highly sensitive to TAK733 with IC50s below 1 nM, while two were considered sensitive with IC50 less than 10 nM." (PMID 22515704, 2012). "These include mutations in NRAS, BRAF, C-KIT (in cutaneous melanoma), GNAQ, and GNA11 (in ocular melanoma), as well as in tumor suppressor genes such as PTEN and p16." (PMID 22220282, 2011). "Conventional chemotherapy is rarely used for treating cutaneous melanomas nowadays but may still be used as a last resort option for BRAF wild-type cases who develop resistance or severe toxicity to immunotherapy." (PMID 40506928, 2025). "This is particularly relevant in OMM, where mutation rates differ significantly from cutaneous melanoma; for instance, KIT mutations may occur in up to 25% of cases, while BRAF mutations are uncommon (<6%)." (PMID 41002705, 2025). "BRAF analysis in 84 patients with stage III or IV cutaneous melanoma." (PMID 40994966, 2025). "Unlike cutaneous melanoma, mucosal melanoma shows BRAF mutations less frequently (10–15%), and these are more commonly non-V600E/K mutations, limiting the applicability of results from the COMBI-AD trial to this group." (PMID 41295253, 2025). "Among patients with stage III–IV cutaneous melanoma tested for BRAF, 47.6% were positive." (PMID 40994966, 2025).
cutaneous melanoma (continued). "Since BRAF V600E/K mutation in mucosal melanoma is less frequent than that in cutaneous melanoma, most of the patients with mucosal melanoma have no treatment options with BRAF/MEK inhibitors." (PMID 39907979, 2025). "Notably, KIT mutations are usually mutually exclusive of BRAF and NRAS mutations, which are the most common oncogenic drivers in cutaneous melanoma." (PMID 41301010, 2025). "The presence of BRAF mutation was not identified in anal mucosal melanomas, but it was observed in 33% of cutaneous melanomas." (PMID 39624501, 2024). "Based on this, we hypothesize that RC48, either alone or in combination with dabrafenib, a clinical stage BRAF inhibitor, may offer improved clinical benefits for patients with BRAF-mutant cutaneous melanoma." (PMID 38594618, 2024). "For example, KRAS essentiality was markedly stronger in KRAS-mutant stomach adenocarcinoma (STAD), rectal adenocarcinoma (READ), pancreatic adenocarcinoma (PAAD) and colon adenocarcinoma (COAD) lineages, whereas BRAF essentiality was strongest in BRAF-mutant skin cutaneous melanoma (SKCM)." (PMID 39009815, 2024). "On the one hand, we have three combinations of targeted therapies (TT) with BRAF-MEK inhibitors (dabrafenib-trametinib, vemurafenib-cobimetinib, and encorafenib-binimetinib) in patients with a BRAF mutation (50% of all subtypes of cutaneous melanoma)." (PMID 38450188, 2024). "Despite recent successes with targeted and immunotherapies in cutaneous melanoma, data on Co-M treated with similar therapies (anti-BRAF/anti-MEK/anti-PDL1) are promising but limited, often stemming from a single patient or small case series with inoperable or advanced disease prior to surgery." (PMID 39335093, 2024). "BRAF mutations in vulval melanomas seems to be less frequent, compared to cutaneous melanomas, probably due to the absence of UV mutational signature in vulval melanomas." (PMID 39104656, 2024). "The differential expression analyses perfomed using GEPIA2 revealed a significantly higher mRNA expression level for LOXL3 and NES in cutaneous melanomas, both with and without confirmed BRAF mutations, compared to normal skin samples." (PMID 39273022, 2024). "BRAF mutations, present in ∼40%–50% of common cutaneous melanomas, are detected in ∼20% AM18,19,20 and are largely absent in MM21,22; thus, only a minority of these patients are suitable for treatment with BRAF&MEK targeting agents." (PMID 38417447, 2024). "ALM has a much lower mutational burden than non-ALM cutaneous melanomas, including a lower incidence of activating mutations in BRAF and NRAS, variable KIT mutations, and a lack of ultraviolet (UV)-related mutational signatures." (PMID 38390259, 2024). "However, the frequency of BRAF, NRAS and Kit mutations in ARM is lower than that of cutaneous melanoma which can also be inferred by our study." (PMID 38180677, 2024). "The aim of this study was to evaluate the therapeutic potential and underlying molecular mechanisms of RC48, a novel HER2-target antibody drug conjugate, either alone or in combination with dabrafenib, a V600-mutant BRAF inhibitor, for the treatment of advanced BRAF-mutant cutaneous melanoma." (PMID 38594618, 2024). "We observed BRAF mutations in just 10 (11.2%) cases, all of which were in V600E GTG>GAG, confirming the previously reported markedly decreased incidence of BRAF mutations in cases of cutaneous melanoma in Ireland." (PMID 38183457, 2024). "In addition to these markers, BRAF V600E immunohistochemical analysis is increasingly performed for primary cutaneous melanomas and metastatic lesions." (PMID 37958863, 2023).
cutaneous melanoma (continued). "Our study showed that MM, as a whole population, had no dominant mutations as comparable as BRAF in cutaneous melanoma." (PMID 37831226, 2023). "BRAF inhibitors are frequently used for human skin melanoma." (PMID 38260202, 2023). "Subsequently, we divided the cutaneous melanoma samples into BRAF wild and BRAF mutant types." (PMID 37745303, 2023). "Patient 5, a 61-year-old man, first presented in May 2019 with an unresectable stage-III cutaneous melanoma, BRAF wildtype, with extensive metastases of the neck." (PMID 35841421, 2023). "Consequently, the FDA and other jurisdictions have approved triplet therapy (BRAFi + MEKi + ICI) as the first‐line treatment for BRAF‐mutant cutaneous melanoma." (PMID 36967556, 2023). "Moreover, only patients with BRAF-mutant tumors, which account for about 50% of all cutaneous melanoma, are eligible for TT with BRAF+MEKi." (PMID 36901733, 2023). "However, genetic evidence argues these tumors mostly originate from cutaneous sites, as they demonstrate a similar distribution of BRAF, NRAS and NF1 mutations to cutaneous melanoma." (PMID 35565222, 2022). "Several large phase 3 randomized studies in cutaneous melanoma with BRAFV600E mutations revealed the advantages of a combination of MEK inhibitors (Cobimetinib or Trametenib) with BRAF inhibitors (Dabrafenib or Vemurafenib) over monotherapy with the BRAF inhibitor." (PMID 35326726, 2022). "Similarities in genetic signatures of mucosal and skin MM suggest similar mechanism of development; however, unlike skin melanoma, there is less BRAF mutation and more of PI3K/AKT/mTOR pathway alterations in mucosal MM." (PMID 36407184, 2022). "Moreover, the tumor diversity with pigmentation status and tumor location provides a comprehensive picture of cutaneous melanoma in a BRAF-driven, MITF-high model." (PMID 34791221, 2022). "Although these tumors did not originate from the uvea of the eye, B16-F10 cells resemble UM in that they are immunotherapy-resistant, do not harbor classical cutaneous melanoma BRAF, NRAS, or NF1 mutations and the TMB is low." (PMID 34753889, 2022). "BRAF mutations are less common in these subtypes – apart from class III mutants that potentiate tighter binding to RAS and CRAF, which are more prevalent in acral and mucosal melanoma than in cutaneous melanoma." (PMID 35234863, 2022). "Cutaneous melanoma is divided into four genomic subtypes: BRAF, NRAS, NF1, and Triple-WT." (PMID 33918490, 2021). "UM rarely harbour mutations in BRAF and is thus not treatable with the BRAF-targeted therapies used in the management of cutaneous melanoma." (PMID 34604096, 2021). "However, the frequency of BRAF and NRAS mutations in acral melanoma is considerably lower than that in cutaneous melanoma, leaving most acral melanoma patients ineligible for treatment with BRAF inhibitors and the combination of BRAF/MEK inhibitors." (PMID 34149718, 2021). "BRAF and NRAS mutations are representative genetic mutations that cause skin melanoma." (PMID 33833342, 2021). "Although a correlation between BRAF mutations and poor prognostic factors has been described in cutaneous melanoma, no predictive value is yet reported for mucosal melanoma." (PMID 34071371, 2021). "BRAF and NRAS mutation frequencies differ between cutaneous melanoma subtypes." (PMID 34680222, 2021). "Given the low rate of BRAF V600 mutation among patients with mucosal melanomas, the combination of BRAF and MEK inhibitors has not led to the same clinical success observed in cutaneous melanoma harboring BRAF activating mutations." (PMID 35008570, 2021). "The distribution of BRAF and NRAS mutation varies according to geographic regions, as observed in cutaneous melanoma, and might explain the better survival observed among European patients in comparison with patients from North America and Asia." (PMID 35008570, 2021).
cutaneous melanoma (continued). "Great support in this direction has been given by the exome sequencing studies of the Cancer Genome Atlas Skin Cutaneous Melanoma (SKCM-TCGA) project that classified cutaneous melanoma into four distinct molecular subtypes: BRAF-mutant, NRAS-mutant, NF1-mutant, and triple-wild-type group." (PMID 34944843, 2021). "It is estimated that about a third of cutaneous melanomas are triple-negative and have no BRAF, NRAS, or NF1 mutations." (PMID 35008286, 2021). "This was a long-term follow-up of Chinese patients with unresectable or metastatic BRAF V600-mutant acral/cutaneous melanoma administered dabrafenib (150 mg twice daily) plus trametinib (2 mg once daily) in an open-label, multicenter, single-arm, phase IIa study (NCT02083354)." (PMID 34504796, 2021). "In TCGA skin cutaneous melanoma (SKCM) patient cohort dataset, where around half of the patients gained BRAF mutations, we investigated whether PRC2 deficiency affects clinical outcomes in patients." (PMID 33713851, 2021). "YAP1 expression was detected in cutaneous melanoma cell lines lacking a GNAQ/11 mutation (but harboring BRAF or NRAS mutations instead), and in human cutaneous melanoma tissue where a high expression was related to worse survival." (PMID 33798262, 2021). "Mutations in BRAF and NRAS are most commonly detected in primary cutaneous melanomas." (PMID 33003469, 2020). "The frequency of BRAF mutations (61.1%) in non-CSD cutaneous melanomas was similar to those described in other publications as 55.2–66.7% in non-CSD." (PMID 32083130, 2020). "Four major genomic subtypes in cutaneous melanoma are BRAF, RAS, NF1, and triple wild-type." (PMID 33256089, 2020). "The disease stage (melanoma of the skin only) was IV in 45.9% (251/547) of patients, the BRAF mutation status was negative in 73.5% (402/547) of patients and 96.9% of patients had a history of prior treatment." (PMID 32515086, 2020). "Notably, dysfunction mutations of NF1 induce BRAF inhibitor resistance by activating RAS and its downstreams including both MAPK and PI3K/AKT/mTOR pathways in cutaneous melanoma." (PMID 32333246, 2020). "Although not statistically significant, the analysis of the different skin melanoma subtypes showed that DDR1 expression is always high for BRAF and NF1 mutants, while there are few outliers with low DDR1 expression for RAS mutants and triple wild-type samples." (PMID 33014862, 2020). "The presence of BRAF mutations might be important in the future because BRAF/MEK inhibitors could possibly play a role in treatment of metastatic disease, as they is used in cutaneous melanoma where BRAF mutations at the same residue are present." (PMID 33396957, 2020). "BRAF class I mutations, consistent with published literature, were the most common mutation identified (39%) and the most predominant among cutaneous melanomas, but not the only class mutation type identified." (PMID 36046072, 2020). "Additionally, these mutations occur independently from mutations of BRAF and NRAS genes, indicating that the pathogenesis of cutaneous melanoma and mucosal melanoma occurs differently." (PMID 31274706, 2020). "It should be noted that regardless of tumor skin site, advanced cutaneous melanoma with a BRAF mutation is eligible for treatment with BRAF inhibitors." (PMID 32282861, 2020). "BRAF and NRAS are common mutation targets in cutaneous melanoma." (PMID 35693877, 2019). "Unlike cutaneous melanoma, uveal melanoma is not characterised by frequent BRAF or NRAS mutations, so that advances in targeted therapy for cutaneous melanoma are not applicable to metastatic uveal melanoma." (PMID 31323802, 2019). "In contrast to cutaneous melanoma, UMs are not BRAF-mutated, thus curtailing the use of B-Raf inhibitors." (PMID 31336679, 2019). "In contrast to cutaneous melanoma (CM), UM does not display any UV mutation signature, and BRAF or NRAS are almost never mutated in primary UM." (PMID 31200439, 2019).
cutaneous melanoma (continued). "Therefore, it can be a good subject for studies to differentiate benign and malignant skin neoplasms, thus predicting tumor behavior and planning specific target therapy by new drugs such as vemurafenib against BRAF V600E." (PMID 31531096, 2019). "As the current knowledge about pathogenesis, clinical and genetic features of cutaneous melanoma is not very clear, we aim to use bioinformatics to identify the potential key genes involved in the expression and mutation status of BRAF." (PMID 30925905, 2019). "A candidate gene approach with 20 cutaneous melanomas found no variant in BRAF, NRAS, PTEN, KIT, GNAQ, and CDK4." (PMID 31262050, 2019). "BRAF V600E was weakly correlated with the Clark level of cutaneous malignant melanoma." (PMID 31531096, 2019). "There is also a subgroup of cutaneous melanomas characterized by a lack of BRAF, N/H/K-RAS, or NF1 mutations, which are referred to as the triple wild-type (TWT) subtype." (PMID 29385676, 2018). "And also, among human cutaneous melanomas, there is a subgroup characterized by the lack of the most common recurring mutations of BRAF, N/H/K-RAS, or NF1, which are referred to as “triple negative” or “triple wild-type” subtype." (PMID 29534457, 2018). "Therefore, our data demonstrate that the cooperation of homozygous Phd2 deletion with oncogenic BRAF leads to the development of primary cutaneous melanoma with lymph node metastatic capacity in mice." (PMID 30575721, 2018). "Metastatic uveal melanoma (MUM) does not harbor typically targetable mutations, e.g., BRAF as in cutaneous melanoma." (PMID 29433557, 2018). "Unlike some of the cutaneous melanomas, uveal melanoma does not harbor BRAF mutations that are the targets of currently available therapies such as vemurafenib or dabrafenib." (PMID 29433557, 2018). "This phenomenon is similar to what has been observed in BRAF WT cutaneous melanoma cell lines." (PMID 28938534, 2017). "Cutaneous melanoma frequently harbors activating mutations in NRAS (around 20%) or the RAS-regulated kinase BRAF (around 37%), suggesting that the RAS-RAF-MAPK pathway may be critical in the pathogenesis of cutaneous melanoma." (PMID 29349077, 2017). "Previous molecular studies showed that cutaneous melanoma has frequent BRAF mutations, but not in CCS." (PMID 28086809, 2017). "Like cutaneous melanoma, CM frequently harbors a BRAF mutation, as opposed to GNAQ/GNA11 mutations which are found in most cases of uveal melanoma." (PMID 28938534, 2017). "A relevant role for NF1 mutations in cutaneous melanomas lacking conventional (i.e. BRAF or NRAS) activating mutations has been already highlighted by other studies." (PMID 28380455, 2017). "BRAF mutations, particularly at codon 600, are found in almost 50% of the cutaneous melanomas, which has led to the successful treatment using BRAF-selective inhibitors, vemurafenib, and dabrafenib, resulting in a prolongation of progression-free and overall survival." (PMID 29290954, 2017). "We highlighted four studies performed by TCGA and Broad Institute of MIT and Harvard Medical School, in which BRAF may be the key driver gene of skin cutaneous melanoma and thyroid carcinomas." (PMID 27746730, 2016). "A large proportion of cutaneous melanomas harbor mutations in genes that are part of the mitogen activated protein kinase (MAPK) pathway (i.e., BRAF and NRAS), which deregulate several important biological processes (proliferation, senescence, survival, and differentiation) in melanocytes." (PMID 27057633, 2016). "Cutaneous melanoma cells but not malignant keratinocytes show oncogenic mutations in either NRAS or BRAF." (PMID 26850723, 2016). "In total, out of the 95 cases (77 oral and 18 cutaneous melanomas), no mutations were found in BRAF, KIT, GNAQ, and CDK4 genes; only three had a positive NRAS mutation and two had a PTEN gene mutation, of which one case had both changes." (PMID 29056717, 2016).